HMGB1 (high mobility group box 1)
Diseases named in the same sentence as HMGB1 in open-access papers (continued):
Sharing a sentence is not in itself a finding about the gene and the disease.
cardiac hypertrophy (29 papers, 2012 to 2025). "Compared with the findings for sham-operated mice, the expression of nuclear HMGB1 in the TAC group was lower, whereas the expression of cytoplasmic HMGB1 was higher, suggesting that the location of HMGB1 in cardiomyocytes may be associated with the progression of cardiac hypertrophy." (PMID 24523730, 2014). "Indirectly, fenofibrate activates PPAR-α to modulate both the expression and location of HMGB1, thus arousing anti-inflammatory response against cardiac hypertrophy." (PMID 36724021, 2023). "Although cardiac nuclear HMGB1 has a protective role in preventing pathological remodeling, exogenous HMGB1 enhances pressure overload-induced cardiac hypertrophy." (PMID 35281739, 2022). "Specifically enriched pathways in malignant spleen and tissues were as following: Two pathways such as HMGB1 signaling and cardiac hypertrophy signaling (Enhanced) were enriched in GSE116347 B16 splenic Treg." (PMID 34084175, 2021). "Previous studies have demonstrated upregulation of TLR4 mRNA and HMGB1 protein in cardiac hypertrophy mice following TAC." (PMID 33324685, 2020). "An increase in TLR4 ligands pool accelerates progression of diseases such as hypertension or cardiac hypertrophy, as well as common ligands such as HSPs, HMGB1, LPS, heparan sulfate (HS), fibrinogen, among others." (PMID 33324685, 2020). "Administration of BoxA in the heart reverses cardiac hypertrophy and delays heart failure (HF) induced by pressure overload, while recombinant HMGB1 aggravates it." (PMID 30306212, 2019). "Neonatal rat cardiomyocytes (NRCM) subject to mechanical stress increase intracellular and extracellular HMGB1 in vitro and this effect is abolished by fenofibrate, an inhibitor of cardiac hypertrophy." (PMID 30306212, 2019). "In line with previous studies 12, 13, we showed that cardiac HMGB1 expression was increased during the pathological process of pressure overload‐induced cardiac hypertrophy, accompanying with its translocation from the nucleus to the cytoplasm." (PMID 26647902, 2016). "The objectives of this study are to determine the role of HMGB1 in cardiac hypertrophy and cardiac dysfunction under pressure overload." (PMID 26647902, 2016). "Exogenous HMGB1 aggravated TAC‐induced cardiac hypertrophy and cardiac dysfunction, as demonstrated by echocardiographic analyses, histological analyses and foetal cardiac genes detection." (PMID 26647902, 2016). "If the endogenous HMGB1 enhances cardiac hypertrophy by binding to RAGE, TAC-induced hypertrophy should be attenuated in RAGE KO mice." (PMID 27355349, 2016). "In the present study, we addressed the potential contribution of local HMGB1 in pressure overload‐induced cardiac hypertrophy and LV dysfunction." (PMID 26647902, 2016). "This study reveals a novel role of fenofibrate in modulating HMGB1 expression and provides a new potential mechanism for fenofibrate in treating cardiac hypertrophy." (PMID 24523730, 2014). "A mouse model of cardiac hypertrophy induced by TAC was used to investigate the expression of both HMGB1 and PPARα in the hearts of the model mice." (PMID 24523730, 2014). "A recent report also showed that, in cardiomyocytes, ET-1 and AngII promoted HMGB1 acetylation and subsequently suppressed the development of cardiac hypertrophy." (PMID 24523730, 2014). "In summary, our data demonstrated that HMGB1 induces cardiac hypertrophy, partially through activation of calcineurin." (PMID 22778498, 2012). "Our findings suggest that HMGB1 leads to cardiac hypertrophy, at least in part through activating calcineurin." (PMID 22778498, 2012). "Particularly, administration of a specific TLR4 blocker, viral inhibitory peptide within the paraventricular nucleus, downregulated HMGB1 in both circulation and brain, and this was accompanied by downregulation of pro-inflammatory cytokines as well as improvement of cardiac hypertrophy." (PMID 33324685, 2020).
cardiac hypertrophy (continued). "Additionally, Bauer and colleagues elucidated the role for HMGB1/TLR4 interaction in driving right ventricular hypertrophy, suggesting that TLR4/HMGB1 axis is involved in the development of cardiac hypertrophy." (PMID 33324685, 2020). "In a cardiac hypertrophy mouse model, myocardial HMGB1 protein expression and translocation from cytoplasm to nucleus were elevated, and overexpression of exogenous HMGB1 produced detrimental effects on myocardium, exacerbating cardiac hypertrophy and LV systolic dysfunction." (PMID 33324685, 2020). "Preservation of intracellular HMGB1 levels prevents cardiac hypertrophy possibly by avoiding oxidative DNA stress, whereas extracellular HMGB1 promotes CM hypertrophy through an unknown receptor." (PMID 30306212, 2019). "In addition, our recent study demonstrated that Ang II-induced HMGB1 secretion is critical for the development of cardiac hypertrophy through RAGE activation." (PMID 31562296, 2019). "Finally, NLRP3 and high-mobility group box-1 (HMGB1) knockdowns reduced cardiac hypertrophy and fibrosis, and restored cardiac function." (PMID 28659798, 2017). "Considering that inflammation is involved in pressure overload-induced cardiac hypertrophy, we herein attempted to investigate whether HMGB1 plays a role in myocardial hypertrophy in RAGE knockout mice as well as in the growth and apoptosis of cardiomyocytes." (PMID 27355349, 2016). "In addition, inhibiting HMGB1 release or promoting nuclear translocation of HMGB1 was also reported to attenuate cardiac hypertrophy." (PMID 27355349, 2016). "Furthermore, fenofibrate protected the storage of the nuclear HMGB1 protein in the heart of mice and suppressed the development of cardiac hypertrophy induced by thoracic transverse aortic constriction." (PMID 27563308, 2016). "Meanwhile, temporary increased LVEF and LV fractional shortening (LVFS) were observed in TAC mice treated with HMGB1, which may be accounted for by the higher extent of cardiac hypertrophy." (PMID 26647902, 2016). "We therefore subsequently determined whether fenofibrate-mediated promotion of HMGB1 translocation from the nucleus to the cytoplasm plays a role in the development of cardiac hypertrophy." (PMID 24523730, 2014). "In addition, we found that nuclear HMGB1 levels decreased in the mice with cardiac hypertrophy and that fenofibrate treatment reversed this decrease and inhibited the development of this disease." (PMID 24523730, 2014). "Because fenofibrate, a peroxisome proliferator-activated receptor α (PPARα) agonist, has shown both protective effects against cardiac hypertrophy and inhibitory effects against inflammation, the potential modulation of HMGB1 expression and secretion by fenofibrate is of great interest." (PMID 24523730, 2014). "Considering that HMGB1 is highly expressed in cardiomyocytes and promotes both cardiac inflammation and cardiac hypertrophy, we hypothesize that HMGB1 is possibly regulated by fenofibrate." (PMID 24523730, 2014). "Altogether, these data suggest that fenofibrate may inhibit the development of cardiac hypertrophy by regulating HMGB1 expression, which provides a new potential strategy to treat cardiac hypertrophy." (PMID 24523730, 2014). "Furthermore, we provide insights into a possible mechanism of how PPARα suppresses the progression of cardiac hypertrophy, with HMGB1 involvement." (PMID 24523730, 2014). "After demonstrating the effect of PPARα on HMGB1 expression and localization in cardiomyocytes, we next investigated whether this effect could influence the progression of cardiac hypertrophy." (PMID 24523730, 2014). "In addition, administration of fenofibrate to mice prevented the development of cardiac hypertrophy induced by thoracic transverse aortic constriction (TAC) while increasing levels of nuclear HMGB1." (PMID 24523730, 2014).
cardiac hypertrophy (continued). "Taken together, these results further support our hypothesis that activation of PPAR by fenofibrate might prevent the development of cardiac hypertrophy by modulating HMGB1 expression and localization." (PMID 24523730, 2014). "In recent years, evidences suggest that high-mobility group box 1 (HMGB1) protein, an inflammatory cytokine, participates in cardiac remodeling; however, the involvement of HMGB1 in the pathogenesis of cardiac hypertrophy remains unknown." (PMID 22778498, 2012). "Thus, HMGB1 may play dual functions in the context of cardiac hypertrophy depending on its subcellular localization." (PMID 30306212, 2019). "However it is unclear which receptor is involved in HMGB1-related cardiac hypertrophy." (PMID 27355349, 2016). "Moreover, exogenous HMGB1 overexpression in myocardium not only promoted pressure overload‐induced cardiac hypertrophy but also aggravated LV systolic dysfunction in the long‐term, which may be reversed by HMGB1 box A, a competitive antagonist of HMGB1." (PMID 26647902, 2016). "This study indicates that the activated and up‐regulated HMGB1 in myocardium, which might partially be derived from cardiac myocytes under pressure overload, may be of crucial importance in pressure overload‐induced cardiac hypertrophy and cardiac dysfunction." (PMID 26647902, 2016). "However, we demonstrated that fenofibrate could prevent the development of cardiac hypertrophy by modulating HMGB1 expression and localization, which also provides a novel approach to the investigation of the pathogenesis of cardiac hypertrophy." (PMID 24523730, 2014). "Therefore, we determined whether cardiac hypertrophy induced by HMGB1 was mediated by the calcineurin-dependent pathway." (PMID 22778498, 2012). "Eight pathways were common between muscle and fat: acute phase signaling, senescence pathway, cardiac hypertrophy, IL-8 signaling, CXCR4 signaling, HMGB1 signaling, GP6 signaling and PDGF signaling." (PMID 33923976, 2021). "Consequently, the TLR4/HMGB1 axis may be a new therapeutic target for cardiac hypertrophy." (PMID 33324685, 2020). "Hypertrophic mediators like angiotensin II or Endothelin-1 induce acetylation and nuclear translocation of HMGB1 in NRCM; conversely, maintenance of stable intracellular HMGB1 levels prevent cardiac hypertrophy." (PMID 30306212, 2019). "In a mice model of pressure overload-induced cardiac hypertrophy by thoracic transverse aortic constriction (TAC), myocardial HMGB1 levels are upregulated because of infiltrating cells and higher expression in cardiomyocytes." (PMID 30306212, 2019). "We found in this study that instead of cardiac hypertrophy, decreased LVEF was observed in mice at 4 weeks after TAC, and exogenous HMGB1 overexpression further aggravated the impairment of cardiac function from this perspective." (PMID 26647902, 2016). "We observed that HMGB1 increased the cellular protein content and ANP expression, two characteristics of cardiac hypertrophy." (PMID 22778498, 2012). "Another study investigated HMGB1 in H9c2 cells, and found that HMGB1 alone had no influence in cardiac hypertrophy but aggravated myocardial hypertrophy in the context of pressure/mechanical stress stimulation, which also caused a prompt upregulation of the expression of TLR4 in cardiomyocytes." (PMID 33324685, 2020). "Fenofibrate attenuates pressure overload-induced cardiac hypertrophy partly by inhibiting the binding of p65-NFκB to NFATc4, the c-Jun NH2-terminal kinase pathway, ERK activation, and MMP2 activity, as well as increasing high mobility group box 1 (HMGB1) levels in nuclei." (PMID 30105051, 2018). "Although our findings in this study can’t answer whether HMGB1-RAGE is involved in any types of cardiac hypertrophy, we can conclude that HMGB1-RAGE is not involved in pressure overload-induced cardiac hypertrophy." (PMID 27355349, 2016).
cardiac hypertrophy (continued). "Additionally, overexpression of HMGB1 alone did not trigger cardiac hypertrophy, but lead to LV dysfunction, along with the decrease in LV thickness." (PMID 26647902, 2016). "The neuroinflammation signaling pathway and HMGB1 signaling pathway were not among the top ten canonical pathways and none of the top 5 canonical pathways from the core analysis of the 8-molecule dataset overlapped with the top 5 canonical pathways from the cardiac hypertrophy with APP dataset." (PMID 33946401, 2021). "In the present study, overexpression of HMGB1 in myocardium alone failed to induce cardiac hypertrophy, but finally resulted not only in the decrease of LV thickness, but in the impairment of LV systolic function, suggesting that HMGB1 may act as a myocardial depressant factor during cardiac injury." (PMID 26647902, 2016). "The ability of HMGB1 to induce cardiac hypertrophy does not involve RAGE, since Rage−/− mice still develop cardiac hypertrophy after TAC." (PMID 30306212, 2019).
subarachnoid hemorrhage (29 papers, 2013 to 2025). A serious neurological disorder characterized by intracranial hemorrhage into the subarachnoid space. "Animal research further indicated that the nuclear translocation of HMGB1 and its subsequent release from the smooth muscle cells of the basilar artery in rats with subarachnoid hemorrhage (SAH) were associated with a persistent vasoconstrictive reaction." (PMID 40877572, 2025). "High mobility group box 1 (HMGB1) protein is a pro-inflammatory-like cytokine with an initiator role in neuroinflammation that has been implicated in Traumatic brain injury (TBI) as well as in early brain injury (EBI) after subarachnoid hemorrhage (SAH)." (PMID 32610502, 2020). "In brain injury caused by subarachnoid haemorrhage, for example, HMGB1 presented with quick translocation and release at 2 hours after injury, resulting in brain damage through the triggering of local inflammation, which was eliminated by the administration of HMGB1 inhibitors." (PMID 30881224, 2019). "Tim‐3 increases HMGB1 levels by inhibiting Nrf2 expression, leading to inflammation following subarachnoid haemorrhage." (PMID 40461955, 2025). "Previously, HMGB1 levels in human CSF have been reported in several diseases, including meningitis, encephalopathy, traumatic brain injury, subarachnoid hemorrhage, and neuromyelitis optica." (PMID 39849347, 2025). "Anti-inflammatory, anti-apoptotic, anti-cholinesterase, and anti-amyloid activities.Protects against subarachnoid hemorrhage by inhibiting the HMGB1/NF-κB pathway." (PMID 38002267, 2023). "In in vitro and in vivo models of experimental subarachnoid haemorrhage, HMGB1 translocation was observed primarily in neurons, whilst HMGB1 translocation events were rare in the glia." (PMID 36551259, 2022). "Oleanoic acid can reduce the level of serum HMGB1 by inhibiting the transfer of HMGB1 from nucleus to cytoplasm, thus reducing early brain injury and neuronal apoptosis after subarachnoid hemorrhage." (PMID 35887090, 2022). "OA exerts a profound protective effect against early brain injury after subarachnoid hemorrhage where the extracellular HMGB1 can induce cytokine release and leukocyte recruitment to trigger inflammatory response." (PMID 35887090, 2022). "Further, oleanolic acid prevented rat model from subarachnoid hemorrhage by SIRT1-modulated HMGB1 deacetylation." (PMID 34906140, 2021). "We reveal that Tim-3 overexpression deteriorates neuroinflammatory and neurocyte apoptosis after subarachnoid hemorrhage through the Nrf2/HMGB1 signaling pathway in rats." (PMID 33168786, 2020). "We searched Pubmed, Ovid medline and Scopus for “subarachnoid hemorrhage” in combination with “HMGB1”." (PMID 32295146, 2020). "Taken together, these results suggest that Tim-3 overexpression appears to deteriorate neuroinflammatory and neurocyte apoptosis after subarachnoid hemorrhage through the Nrf2/HMGB1 signaling pathway in rats." (PMID 33168786, 2020). "This review emphasizes the importance of pharmacological interventions targeting high mobility group box 1 (HMGB1)-mediated brain damage after subarachnoid hemorrhage (SAH) and CVS." (PMID 32295146, 2020). "Anti-HMGB1 antibody has been shown to be useful for prevention of brain edema, ischemic brain injury, and delayed cerebral vasospasm after subarachnoid hemorrhage." (PMID 29699567, 2018). "Many studies have shown that HMGB1 is released by neurons during subarachnoid hemorrhage and cerebral ischemia disease." (PMID 30013568, 2018). "HMGB1, known to be essential for ischemic brain injury, is reported to be upregulated in the microglia after subarachnoid hemorrhage, and the HMGB1 inhibitor glycyrrhizin attenuates ICH-induced brain injury." (PMID 23414417, 2013). "Intervention using an anti-HMGB1 monoclonal antibody notably alleviated the severity of vasospasm and inhibited inflammatory responses within the arterial vascular wall subsequent to subarachnoid hemorrhage (SA)." (PMID 40877572, 2025).
subarachnoid hemorrhage (continued). "This hypothesis is supported by a study involving cerebral vasospasm secondary to subarachnoid hemorrhage in rats, which reported a reduction of intracellular peptide and mRNA expression of HMGB-1 in rat basilar artery after Glyz treatment." (PMID 37513606, 2023). "We evaluated the therapeutic effects of bone-marrow-derived mesenchymal stem cells (BMSCs) on behavioral and cognitive function in a mouse model of mild subarachnoid hemorrhage (SAH) and explored the underlying mechanisms in conjunction with the HMGB1–RAGE axis." (PMID 37109411, 2023). "Furthermore, an experimental model of subarachnoid hemorrhage (SAH) confirmed HMGB1 upregulation and showed that HMGB1 was translocated into the cytosol of the microglia for active secretion." (PMID 32295146, 2020). "Furthermore, the subarachnoid hemorrhage injury could be improved by suppressing the high mobility group box 1 (HMGB1)/NF-κB pathway." (PMID 35284463, 2022). "Overexpression of extracellular HMGB1 has been observed in several neuroinflammatory conditions, including TBI, subarachnoid hemorrhage (SAH) and neurodegenerative diseases." (PMID 37048161, 2023). "In addition, GL may inhibit high-mobility group protein B1 (HMGB1) expression and subsequent production of inflammatory cytokines to prevent cerebral vasospasm (CVS) following subarachnoid hemorrhage (SAH) in Sprague-Dawley rats." (PMID 32867101, 2020).